RNU5B-1 (RNA, U5B small nuclear 1)
Synonyms: U5B1; NEDSJL; RNU5B; RNU5B-1P
Gene: Small nuclear RNA gene on chromosome 15 (65,304,677 to 65,304,793, forward strand). Ensembl gene ENSG00000200156.
Gene Ontology:
Biological process: formation of quadruple SL/U4/U5/U6 snRNP; spliceosomal tri-snRNP complex assembly
Cellular component: U4/U6 x U5 tri-snRNP complex; U5 snRNP
Gene-disease validity (ClinGen):
ClinGen rates the evidence that RNU5B-1 causes each of these diseases.
RNU5B-1 related neurodevelopmental disorder with seizures and joint laxity (autosomal dominant): Strong.
Diseases named in the same sentence as RNU5B-1 in open-access papers:
RNU5B-1 is named in the same sentence as 5 diseases in open-access papers, as found by Europe PMC text mining. Sharing a sentence is not in itself a finding about the gene and the disease. The quoted sentences say what the papers report.
developmental delay (1 paper, 2025). "We collected detailed clinical information from five individuals with rare RNU5B-1 variants in our cohort, which revealed that the ‘RNU5B-1-related disorder’ is characterized by global developmental delay, relative macrocephaly, seizures and failure to thrive." (PMID 40442284, 2025). "RNU5B-1-related disorder is characterized by global developmental delay, hypotonia, macrocephaly and failure to thrive." (PMID 40442284, 2025).
ReNU syndrome (1 paper, 2026). "De novo variants in snRNA genes RNU4-2 (ReNU syndrome), RNU5B-1 and RNU2-2 have been linked to dominant neurodevelopmental disorders (NDDs), revealing a large unexpected contribution of noncoding RNA genes to genetic diseases." (PMID 41912934, 2026).
neurodevelopmental disorder (2 papers, 2025 to 2026). A behavioral and cognitive disorder with onset during the developmental period that involves impaired or aberrant development of intellectual, motor, or social functions. "Genomic analyses focused on regions that form R-loops identify rare mutations in RNU2-2 and RNU5B-1 in individuals with neurodevelopmental disorders." (PMID 40442284, 2025). "We implicate rare variants in RNU2-2 and RNU5B-1 as causes for neurodevelopmental disorders (NDDs)." (PMID 40442284, 2025). "Using this insight, we report neurodevelopmental disorders (NDDs) caused by rare variants in two major spliceosomal RNA encoding genes, RNU2-2 and RNU5B-1." (PMID 40442284, 2025).
RNU5B-1 also shares sentences with these, for which no sentence is quoted: Failure to thrive (1 paper); genetic diseases (1).